ALYREF (Aly/REF export factor)
Diseases named in the same sentence as ALYREF in open-access papers (continued):
Sharing a sentence is not in itself a finding about the gene and the disease.
gastric cancer (3 papers, 2020 to 2024). A primary or metastatic malignant neoplasm involving the stomach. "We further analyzed the co-expressed genes as well as mutations in all patients with gastric cancer and their correlation with ALYREF level." (PMID 38491127, 2024). "In vitro, knockdown of ALYREF suppressed the cell proliferation and foci formation in gastric cancer indicating the potential carcinogenic function of ALYREF on carcinogenesis." (PMID 38491127, 2024). "Subsequently, we conducted in vitro function experiments to validate the results, demonstrating that knockdown of ALYREF inhibited cell proliferation, arrested cell cycle and induced cell apoptosis in the gastric cancer cell line AGS." (PMID 38491127, 2024). "Under Lauren classification, ALYREF highly expressed in diffuse-type gastric cancer compared with intestinal-type gastric cancer (p < 0.01)." (PMID 38491127, 2024). "And then, we conducted biological experiments to reveal the actual effect of ALYREF on gastric cancer cells." (PMID 38491127, 2024). "Furthermore, prognostic analysis of different molecular subtypes of gastric cancer unfolded that high ALYREF expression in MSI GC patients leading to poor prognosis (p < 0.01)." (PMID 38491127, 2024). "Our results implied that ALYREF could be considered as a promising prognostic biomarker and therapeutic target for gastric cancer." (PMID 38491127, 2024). "Prognostic analysis of different molecular subtypes of gastric cancer (GC) unfolded that high ALYREF expression leads to poor prognosis in certain subtypes of GC." (PMID 38491127, 2024).
urothelial carcinoma of the bladder (3 papers, 2024 to 2025). "Mechanistically, high ALYREF expression can promote bladder urothelial carcinoma (BLCA) proliferation by regulating PKM2‐mediated glycolysis." (PMID 38572667, 2024). "Additionally, ALYREF contributes to the malignancy of urothelial carcinoma of the bladder (UCB) by maintaining the stability of RABL6 and TK1 mRNA30." (PMID 38491127, 2024). "Previous studies have shown that both ALYREF and NSUN2 are upregulated in urothelial carcinoma of the bladder, suggesting a possible synergistic effect." (PMID 41345330, 2025).
pancreatic ductal adenocarcinoma (2 papers, 2024 to 2025). An infiltrating adenocarcinoma that arises from the epithelial cells of the pancreas. "Recently, ectopic expression of ALYREF was found to induce immune evasion in pancreatic ductal adenocarcinoma." (PMID 39915011, 2025).
retinoblastoma (2 papers, 2021 to 2024). A malignant tumor that originates in the nuclear layer of the retina. "In retinoblastoma (RB), the NSUN2/ALYREF/m5C-PFAS carcinogenic cascade is an important trigger of RB and can promote purine synthesis during the pathological process." (PMID 38764010, 2024).
acute myeloid leukemia (1 paper, 2016). Acute myeloid leukemia (AML) is a group of neoplasms arising from precursor cells committed to the myeloid cell-line differentiation. "ALYREF was originally described as a transcriptional coactivator of the T-cell receptor α gene by binding LEF-1 and acute myeloid leukemia (AML)-1 transcription factors to form an enhancer-stimulating complex." (PMID 27679854, 2016).
breast tumor (1 paper, 2022). "Moreover, as we found that inducible knock-down of target ALYREF expression in orthotopic breast tumors led to significantly decreased tumor formation, these findings indicate the potential for therapeutic interventions to treat TNBC." (PMID 35776213, 2022). "This work establishes ALYREF as a potential prognostic factor in TNBC and demonstrates that ALYREF is important in breast tumor formation, at least in part, through the transcriptional and post-transcriptional regulation of the short NEAT1 isoform." (PMID 35776213, 2022).
cervical cancer (1 paper, 2024). A primary or metastatic malignant neoplasm involving the cervix. "Collectively, our data provided novel evidence that NSUN6/ALYREF-mediated m5C modification maintained the stability of NDRG1 mRNA in cervical cancer." (PMID 38970106, 2024). "Thus, our findings illustrate a regulatory mechanism of RNA m5C-mediated radioresistance and provide a therapeutic rationale for targeting the NSUN6/ALYREF-m5C-NDRG1 signaling axis in cervical cancer." (PMID 38970106, 2024).
epilepsy (1 paper, 2023). A brain disorder characterized by episodes of abnormally increased neuronal discharge resulting in transient episodes of sensory or motor neurological dysfunction, or psychic dysfunction. "Therefore, further studies on the ALYREF protein are regarded as having the potential to provide insight into epilepsy and potential novel therapeutic strategies." (PMID 36980356, 2023).
fibrolamellar carcinoma (1 paper, 2021). "ALYREF expression was significantly increased in HCC tissues compared to normal tissues, and its expression in fibrolamellar carcinoma was higher compared to that of hepatocholangio carcinoma (mixed)." (PMID 34367948, 2021).
gallbladder cancer (1 paper, 2025). "RT-qPCR analysis demonstrated significant upregulation of ALYREF expression in Gallbladder Cancer (GBC) tissues relative to adjacent normal tissues, with corresponding elevation observed in NOZ and GBC-SD cell lines compared to HIBEpiCs." (PMID 40466438, 2025).
Immunodeficiency (1 paper, 2024). Failure of the immune system to protect the body adequately from infection, due to the absence or insufficiency of some component process or substance. "Given that this gene is upregulated in most cancers, including LUSC, we suggest that ALYREF could contribute to the formation of immunodeficiency niches by reducing the number of tumor-infiltrating cells, thus exacerbating LUSC progression." (PMID 38361753, 2024).
intellectual disabilities (1 paper, 2023). "ALYREF has been described as the main regulator of m5C-modified mRNA export out of the nucleus, and mutations within transcription and export (TREX) complex proteins involved in the export process cause syndromic forms of intellectual disabilities." (PMID 36646969, 2023).
invasive breast carcinoma (1 paper, 2022). A carcinoma that infiltrates the breast parenchyma. "Additional TMA tissue microarray IHC analysis of ALYREF expression demonstrates highly increased ALYREF expression in invasive breast carcinoma samples (n = 100) when compared to adjacent normal breast tissue (n = 10)." (PMID 35776213, 2022).
leukoplakia (1 paper, 2021). A white patch or plaque on a mucous membrane that cannot be characterized clinically or pathologically as any other disease. "The expression of three m5C regulators—NOP2, DNMT3B, and ALYREF—was upregulated in oral leukoplakia patients from two microarray datasets, GSE26549 and GSE85195." (PMID 34957065, 2021).
pancreatic cancers (1 paper, 2025). "Studies have revealed abnormal expression patterns of m5C methyltransferases, including NSUN2 and NSUN6, as well as m5C-binding proteins like YBX1 and ALYREF, in cancers such as esophageal, gastric, hepatocellular, colorectal, and pancreatic cancers." (PMID 40114967, 2025). "Regression analysis indicates that ALYREF and NSUN6 function as independent prognostic biomarkers for predicting pancreatic cancer outcomes." (PMID 40114967, 2025). "In pancreatic cancer tissues, NSUN2 and ALYREF are significantly upregulated, with NSUN2 expression positively correlating with TNM stage and distant metastasis Elevated levels of NSUN2 and ALYREF are associated with shorter OS in patients with pancreatic cancer." (PMID 40114967, 2025). "Additionally, ALYREF has been shown to promote tumor growth and increase Ki-67 expression in tumor tissues, while NSUN6 inhibits pancreatic cancer cell proliferation and in vivo tumor growth." (PMID 40114967, 2025).
paraganglioma (1 paper, 2024). A benign or malignant neoplasm arising from paraganglia located along the sympathetic or parasympathetic nerves. "Thyroid carcinoma (THCA) and pheochromocytoma and paraganglioma (PCPG) were the only two cancers without an apparent difference in ALYREF expression." (PMID 38491127, 2024).
sarcoma (1 paper, 2024). A usually aggressive malignant neoplasm of the soft tissue or bone. "By analyzing the most conserved motifs, such as CGGGAG, RNA binding proteins Aly/REF export factor (ALYREF) and fused in sarcoma (FUS) were identified to promote miRNA enrichment in exosomes via these motifs." (PMID 38448424, 2024).
stomach adenocarcinoma (1 paper, 2024). "Specially, expression level of ALYREF were strongly positively correlated with all four indices in stomach adenocarcinoma (STAD)." (PMID 38491127, 2024).
triple-negative breast carcinoma (1 paper, 2022). An invasive breast carcinoma which is negative for expression of estrogen receptor (ER), progesterone receptor (PR), and human epidermal growth factor receptor 2 (HER2). "Thus, we also assessed the expression of DNMT3B and ALYREF in luminal, HER2 positive, and triple negative breast cancer." (PMID 35812757, 2022).
tumor (56 papers, 2016 to 2026). "Rescue experiments in which ALYREF silencing reversed the effects of circRREB1 overexpression further confirmed the causal link between this pathway and the tumour-promoting function of circRREB1." (PMID 40653497, 2025). "Our results showed that NSUN2, DNMT1, DNMT3A, DNMT3B, TRDMT, and ALYREF were related to high or low tumor risk, while NOP2 was related to the pTNM stage of tumors." (PMID 38579085, 2024). "The GSEA results indicated that ALYREF knockdown inhibited the expression of genes associated with tumor metastasis." (PMID 39117671, 2024). "We demonstrated that the expression of ALYREF was significantly increased in the tumor tissues of pan-cancer and was associated with clinical poor prognosis." (PMID 38491127, 2024). "ALYREF expression was significantly related to Tumor mutational burden (TMB) in four cancer types (3 positively related) and to Microsatellite Instability (MSI) in three tumors (2 positively related)." (PMID 38491127, 2024). "Four m5C/m6A-related gene signatures consisting of HNRNPA2B1, IGF2BP2, NSUN4, and ALYREF were used to construct a prognostic risk model, and the high-risk group had a worse prognosis, higher immune checkpoint expression, and tumor mutational burden (TMB)." (PMID 36246622, 2022). "Pan-cancer analysis showed that ALYREF overexpression was significantly associated with advanced tumor-lymph node metastasis stage and poor HCC prognosis, so the constructed immune prognostic model could effectively evaluate patients." (PMID 41180455, 2025). "In addition, both NOP2 and ALYREF were associated with tumor migration, and NOP2 was related to the pT stage of the tumors." (PMID 38579085, 2024). "ALYREF knockdown phenocopied the tumor-suppressive effects of circHIPK3 depletion, whereas ALYREF overexpression rescued circHIPK3 knockdown-induced suppression of malignant phenotypes." (PMID 40466438, 2025). "The remaining tumours also showed strongly reduced nuclear ALYREF levels in tumour tissues of the RNF31 knockdown and IPO13 knockdown groups, as detected by western blotting and IHC assays." (PMID 39915011, 2025). "The interaction between ALYREF and m5C-modified RNA enhances both the stability and translational efficiency of the RNA, a function particularly critical in tumor cells." (PMID 40114967, 2025). "Consistent with this, as an m5C reader protein, ALYREF has been found in various types of tumors to promote tumor progression by mediating the nucleocytoplasmic transport of substrate mRNAs 50-52." (PMID 40083919, 2025). "Recent reports showed that upregulated ALYREF correlated with tumour growth, disease progression, immune evasion, and poor survival." (PMID 39915011, 2025). "Accumulating evidence indicates that ALYREF expression correlates markedly with tumour growth and drug resistance." (PMID 39915011, 2025). "The binding of ALYREF to YAP1 mRNA inhibits the apoptosis of tumour cells through activation of the Hippo and Wnt/β-catenin pathways." (PMID 40860147, 2025). "Pan-cancer analysis revealed that RNA methylation genes ALYREF, NSUN4, TRMT6, and YTHDF1 were associated with immune infiltration in the tumor microenvironment." (PMID 41244907, 2025). "To further examine the function of ALYREF in tumor formation in vivo, we used HepG2 cells to construct a xenograft mouse tumor model." (PMID 38164181, 2024). "Previous studies have implied a potential function of ALYREF in facilitating the export of m5C-modified mRNAs, as well as its possible role as a positive regulator of tumor growth and metastasis in cancer cell lines." (PMID 39117671, 2024). "Our study found that ALYREF shows the most significant differences between tumor samples and normal tissues and the overexpression of ALYREF is a marker of bad prognosis." (PMID 38402198, 2024).
tumor (continued). "GO and KEGG analysis showed that ALYREF to be essential in regulating the cell cycle and gene mismatch repair in tumor progression." (PMID 38491127, 2024). "Due to the importance of ALYREF in tumor development, the relationship between ALYREF expression level and drug sensitivity was studied using CellMiner data." (PMID 38491127, 2024). "To understand the interactions between the expression of m5C readers and the tumor microenvironment, we analyzed the correlations between expression of ALYREF and YBX1 and various immune cell populations." (PMID 38238581, 2024). "The results of KEGG and GO analysis indicated that ALYREF is essential in regulating the cell cycle and mismatch repair in tumor progression." (PMID 38491127, 2024). "In this study, correlation analyses between ALYREF expression and immunomodulatory genes, immune checkpoints, and tumor-infiltrating cells showed consistent results." (PMID 38361753, 2024). "In these tumor types, high expression of ALYREF and YBX1 is observed in advanced pathologic TNM stages as well as clinical grade." (PMID 38238581, 2024). "We analyzed the expression levels of ALYREF in tumor microenvironment-related cells using TIMER, EPIC, QUANTISEQ, and MCPCOUNTER databases." (PMID 38579085, 2024). "We observed differential ALYREF expression between tumor and normal samples, correlating strongly with prognosis in various cancers, particularly kidney renal papillary cell carcinoma (KIRP) and liver hepatocellular carcinoma (LIHC)." (PMID 38361753, 2024). "In m5C-dependent regulation, writer NOP2/Sun RNA Methyltransferase 2 (NSUN2) plays crucial roles in tumor progression, Aly/REF export factor (ALYREF) considered as a reader of mRNA m5C facilitates the export of RNA from the nucleus to the cytoplasm." (PMID 38491127, 2024). "We found that higher expression of ALYREF mRNA tended to have a more advanced tumor classification and TNM stage both in TCGA-LIHC cohorts and in our 3 LIHC cohorts." (PMID 38164181, 2024). "Further exploration of the function of ALYREF in STAD is absolutely necessary for clarifying the kind of role it plays in tumor heterogeneity and MSI in STAD." (PMID 38491127, 2024). "In the context of tumor stemness, ALYREF was significantly correlated with LGG (r = 0.15), LUAD (r = 0.49), ESCA (r = 0.48), PRAD (r = 0.10), LUSC (r = 0.56), LIHC (r = 0.37), MESO (r = 0.31), BLCA (r = 0.37), ACC (r = 0.24), and DLBC (r = 0.57) for RNAss." (PMID 38361753, 2024). "We discovered significant correlations between ALYREF expression and various aspects of tumor heterogeneity and stemness." (PMID 38361753, 2024). "We found that the expression levels of ALYREF in the tumor microenvironment-related cells of BLCA were distinctly correlated with the TIM, which is why the other 8 different m5C regulators were not related to prognosis." (PMID 38579085, 2024). "After knockdown of ALYREF, the inhibited colony formation and subcutaneous tumor formation were partially rescued by expressing RABL6 with WT m5C-site." (PMID 36806253, 2023). "Mechanistically, NSUN3 promotes tumor progression by regulating immune infiltration, and ALYREF enhances mitochondrial activity and intracellular energy metabolism, which ensures continuous energy supplies for timorous tissues." (PMID 37325635, 2023). "Our findings with ALYREF knockdown recapitulated some of the speckle signature group differences in ccRCC tumor samples." (PMID 37745397, 2023). "After knockdown of ALYREF, the inhibited colony formation and subcutaneous tumor formation were partially rescued by expressing TK1 with WT m5C-site." (PMID 36806253, 2023). "LINC01259 and ALYREF were highly expressed and positively correlated in tumor tissues of NSCLC patients and high levels of ALYREF predicted an adverse outcome in NSCLC patients." (PMID 37537569, 2023). "Recent studies have shown that ALYREF is involved in tumor cell proliferation, metabolism, and metastasis." (PMID 37537569, 2023).